IGFBP1 (insulin like growth factor binding protein 1)
Diseases named in the same sentence as IGFBP1 in open-access papers (continued):
Sharing a sentence is not in itself a finding about the gene and the disease.
type 2 diabetes (42 papers, 2011 to 2025). "Wallander and colleagues also demonstrated that high IGFBP-1 levels were linked to increased cardiovascular morbidity and mortality in patients with type 2 diabetes following MI." (PMID 40710778, 2025). "An upward shift in the relationship between IGFBP-1 and insulin has previously been reported in older men (63–81 years compared to 20–39 years), in GH deficiency and type 1 diabetes, and in type 2 diabetes." (PMID 40188287, 2025). "Our feature selection approach identified several validated biomarkers that have already been shown to be associated with type 2 diabetes risk, including mannose, glycine and IGFBP-1, among others." (PMID 37889320, 2024). "In adults with established type 2 diabetes, lower IGFBP-1 remains associated with cardiovascular risk factors including fasting insulin, LDL cholesterol and BMI." (PMID 39595651, 2024). "Igfbp1 is an endogenous promoter of β-cell regeneration and reduces the risk of developing type 2 diabetes." (PMID 36936413, 2023). "Odds ratios (ORs) for decreasing values of IGFBP-2, adiponectin and IGFBP-1 measured at baseline and included in the same regression model in the association to development of prediabetes and type 2 diabetes at follow-up in women and men." (PMID 36686443, 2022). "Lower levels of IGFBP-1 in the circulation predict type 2 diabetes, the metabolic syndrome and the risk of developing cardiovascular disease." (PMID 33758952, 2021). "A decrease of IGF-1 and an increase of IGFBP1 was moreover associated with increased risk of developing cardiac failure in older people with type 2 diabetes." (PMID 33686453, 2021). "Obese subjects and people with type 2 diabetes had lower levels of IGFBP1 and weight loss, as well as exercise increased levels of IGFBP1." (PMID 33686453, 2021). "This has also been confirmed with recent findings from a large prospective study again suggesting that IGFBP-1 levels have a strong inverse associations with risk of type 2 diabetes risk in women." (PMID 30392760, 2019). "Clinical investigations have demonstrated that low circulating levels of IGFBP-1 are associated with type 2 diabetes (T2D), whereas high serum IGFBP-1 levels are associated with T1D." (PMID 24904693, 2014). "Prospective studies have shown that low levels of circulating insulin-like growth factor binding protein-1 (IGFBP-1) are associated with the risk of type 2 diabetes." (PMID 24246027, 2013). "Our study demonstrates that increased IGFBP1 methylation levels and reduced protein levels are associated with type 2 diabetes." (PMID 24246027, 2013). "In this study, we provide the first evidence that DNA methylation changes of the IGFBP1 gene are associated with type 2 diabetes in Swedish men with a short duration." (PMID 24246027, 2013). "Interestingly, in adulthood, low IGFBP-1 levels are associated with a higher risk for type 2 diabetes." (PMID 38831310, 2024). "Recent studies indicate that changes in DNA methylation of the insulin-like growth factor binding protein-1 (IGFBP1) gene are associated with type 2 diabetes, suggesting that increased IGFBP1 DNA methylation and decreased IGFBP1 serum levels are features of short-duration type 2 diabetes." (PMID 26703582, 2015). "It is unknown whether DNA methylation patterns of the IGFBP1 gene are associated with type 2 diabetes." (PMID 24246027, 2013). "Previous studies have reported altered IGFBP-1 levels in patients with type 2 diabetes, with several studies describing increased concentrations, while others have demonstrated decreased levels depending on patient characteristics." (PMID 41226444, 2025). "Conversely, when insulin levels are low (during fasting or in the late stages of type 2 diabetes), elevated IGFBP-1 levels inhibit IGF-I mediated effects." (PMID 36901984, 2023). "For example, in patients with type 2 diabetes (n = 74), low serum IGFBP-1 (s-IGFBP-1) was correlated with cardiovascular risk factors." (PMID 37298072, 2023).
type 2 diabetes (continued). "IGFBP-1 is higher in individuals with type 1 diabetes (hypoinsulinemic), decreased in those with type 2 diabetes (hyperinsulinemic), and significantly diminished by insulin administration." (PMID 35586622, 2022). "In a prospective study with 17 years of follow-up, low IGFBP-1 levels strongly predicted the long-term development of type 2 diabetes." (PMID 32190801, 2020). "Because IGFBP1 expression is strongly regulated by insulin, it serves as an excellent marker of IR in type 2 diabetes patients." (PMID 29777116, 2018). "Insulin plays a key role in these changes and also inhibits IGFBP-1: low levels predict the development of disturbances in glucose homeostasis including type 2 diabetes several years later." (PMID 26237614, 2014). "In the progression to type 2 diabetes, IGFBP-1 is less suppressed and is inappropriately high in relation to the prevailing insulin concentrations." (PMID 26237614, 2014). "In the present study, we investigated DNA methylation in the IGFBP1 gene to evaluate its changes in relation to serum IGFBP-1 levels in type 2 diabetes." (PMID 24246027, 2013). "In this study, we investigated DNA methylation levels of the IGFBP1 gene in Swedish men, including subjects with normal glucose tolerance or type 2 diabetes and analysed serum IGFBP-1 levels." (PMID 24246027, 2013). "In prospective epidemiological studies on men and women with normal oral glucose tolerance test (OGTT), low IGFBP1 predicts the development of type 2 diabetes within a decade." (PMID 23781317, 2013). "Serum levels of IGFBP-1 in newly diagnosed and in treated type 2 diabetes patients were lower compared with healthy individuals (18 μg/l both vs. 24 μg/l, P = 0.011, P < 0.001)." (PMID 24246027, 2013). "We found increased DNA methylation in all type 2 diabetes patients, who also had decreased circulating levels of IGFBP-1." (PMID 24246027, 2013). "Taking our present study and recent reports together, we also suggest that increased IGFBP1 DNA methylation and decreased IGFBP-1 serum levels are features of type 2 diabetes." (PMID 24246027, 2013). "We have also demonstrated that a low serum level of IGFBP-1 predicts the development of type 2 diabetes in middle-aged Swedish men and women." (PMID 24246027, 2013). "Pathologically, the expression of IGFBP-1 is elevated type 2 diabetes and some cancer patients." (PMID 38246959, 2024). "In fact, the prediabetic group differed from the high-risk groups identified in cross-sectional or prospective observational studies with regard to IGFBP-1; according to a Swedish study, an increase in IGFBP-1 was observed in individuals with prediabetes as they approached overt type 2 diabetes." (PMID 38928106, 2024). "Low IGFBP-1 is a predictor of prediabetes and type 2 diabetes." (PMID 39595651, 2024). "Likewise, low levels of IGFBP1 have been reported to predict the development of type 2 diabetes and IGFBP1 has been proposed as a potential marker of insulin sensitivity." (PMID 36498997, 2022). "Furthermore, disruptions to IGFBP-1 have also been associated with diabetic nephropathy, with polymorphisms in IGFBP-1 associated with kidney disease in type 2 diabetes." (PMID 33758952, 2021). "In the LEGUAN study, we addressed the question whether the protein source in a high-protein diet, animal- vs. plant-based protein, is a relevant determinant of circulating IGF-1, IGFBP1 and 2 levels in participants with type 2 diabetes." (PMID 33686453, 2021). "Clinical data from diverse populations suggest that low levels of IGFBP-1 may be permissive for the development of type 2 diabetes in humans." (PMID 32190801, 2020). "Similarly, a 17 year follow up of 782 patients, showed that a low IGFBP-1 predicts the development of type 2 diabetes." (PMID 30392760, 2019). "Altered patterns of IGFBP-1 multimerisation have been reported in type 2 diabetes." (PMID 26237614, 2014).
type 2 diabetes (continued). "Fasting IGFBP-1 is a good predictive marker of abnormal glucose homeostasis, with low values predicting the development of impaired fasting glucose, impaired glucose tolerance and type 2 diabetes 8–17 years later." (PMID 26237614, 2014). "In both men and women, at the time of diagnosis of type 2 diabetes, fasting IGFBP-1 may rise in relation to insulin, which may be in part due to hepatic insulin resistance." (PMID 26237614, 2014). "To further investigate whether changes of IGFBP1 DNA methylation levels were related to body weight in type 2 diabetes, we conducted analyses according to body mass index (BMI)." (PMID 24246027, 2013). "Low IGF-binding protein 1 (IGFBP1) can predict the development of type 2 diabetes." (PMID 23781317, 2013). "Thus, we were able to confirm decreased levels of IGF-1 and increased levels of IGFBP-1 in type 2 diabetes patients with nephropathy." (PMID 22400116, 2012). "Clinical observations have demonstrated that high levels of circulating insulin-like growth factor binding protein-1 (IGFBP-1) are associated with type 1 diabetes (T1D), whereas low serum IGFBP-1 levels are associated with the risk of type 2 diabetes (T2D)." (PMID 24904693, 2014). "However, we were not able to establish the causal relationship between IGFBP1 DNA methylation alteration and the development of type 2 diabetes from the current cross-sectional study." (PMID 24246027, 2013). "Combining all six CpG sites together, the mean values of IGFBP1 DNA methylation levels were significantly increased in both newly diagnosed and treated patients in comparison with non-diabetic subjects (19.8%, 18.9% and 16.9%, P < 0.001 for both type 2 diabetes groups vs. controls)." (PMID 24246027, 2013). "Here, we study the power of the biomarkers adiponectin, IGFBP-1, IGFBP-2, and also included IGF-I and IGF-II, in predicting prediabetes and type 2 diabetes (T2D) in men and women with normal oral glucose tolerance (NGT)." (PMID 36686443, 2022). "This demonstrates that decreased IGFBP-1 in obese/overweight children is simply not a consequence of increased fatness/adiposity, but it may reflect other independent metabolic processes conveying higher risk for dyslipidemia and type 2 diabetes." (PMID 35586622, 2022). "We, therefore, evaluated the effects of animal versus plant protein-enriched diets (30% protein, 40% carbohydrates, 30% fat) in older patients with type 2 diabetes on circulating IGF-1, IGFBP1 and IGFBP2 levels." (PMID 33686453, 2021). "When evaluating IGFBP1 DNA methylation levels in type 2 diabetes patients according to FHD, we found that newly diagnosed patients with FHD not only had higher fasting glucose and insulin levels but also increased IGFBP1 DNA methylation." (PMID 24246027, 2013). "In contrast, UNC5D, ST3GAL6, SCG3, and IGFBP1, which are negatively affected by noisy workplace environments, are potentially protective factors against coronary heart disease (UNC5D), type 2 diabetes (UNC5D), tinnitus (ST3GAL6, SCG3), and rheumatoid arthritis (IGFBP1)." (PMID 35602164, 2022). "The 24‐hr response profiles for TAG, NEFA, bHB, and IGFBP‐1 were obtained when ingesting a mixed control diet before, and during the last 48–72 hr when ingesting a CHO‐free diet or fasting in male subjects with untreated type 2 diabetes." (PMID 33030304, 2020). "This study provides the first evidence that changes in DNA methylation of the IGFBP1 gene are associated with type 2 diabetes in Swedish men and suggests that increased IGFBP1 DNA methylation and decreased IGFBP-1 serum levels are features of type 2 diabetes with a short duration." (PMID 24246027, 2013). "Our results demonstrated that compared with non-diabetic controls, DNA methylation levels of the IGFBP1 gene were higher in all type 2 diabetes patients, while IGFBP-1 serum levels were lower." (PMID 24246027, 2013).
type 2 diabetes (continued). "We conducted an epigenetic study of the human IGFBP1 gene in Swedish men with and without type 2 diabetes in parallel with analyses of fasting IGFBP-1 protein levels in serum." (PMID 24246027, 2013). "Newly diagnosed type 2 diabetes patients with FHD had significantly increased IGFBP1 DNA methylation levels compared with the patients without FHD (20.3% vs. 18.6%, P = 0.017)." (PMID 24246027, 2013). "IGFBP1 methylation levels but not serum IGFBP-1 levels in type 2 diabetes patients were independent of body mass index." (PMID 24246027, 2013). "It is possible that an increase in IGFBP2 concentrations occurs in type 2 diabetes followed by an increase in local IGF1 and IGF2 concentrations in the renal glomerulus, very similar to the hypothesis postulated for IGF1 and IGFBP1 interaction in nephropathy." (PMID 23781310, 2012). "A borderline significant correlation between IGFBP1 DNA methylation levels and IGFBP-1 serum levels was found in non-diabetic subjects (r = 0.186, P = 0.050), but not in newly diagnosed type 2 diabetes patients (P = 0.770) or patients undergoing treatment (P = 0.230)." (PMID 24246027, 2013). "However, there are no reports from epigenetic studies of IGFBP1 in type 2 diabetes." (PMID 24246027, 2013). "The correlation between DNA methylation and serum protein levels is influenced by multiple factors, which may explain the lack of correlation between IGFBP1 DNA methylation and serum IGFBP-1 levels in type 2 diabetes patients." (PMID 24246027, 2013).
breast carcinoma (39 papers, 1996 to 2025). "Until know, the only functions associated with IGFBP-1 in tamoxifen treated breast cancer cells have focused on the extracellular role of this protein." (PMID 32435229, 2020). "One possible mechanism that underlies the prosurvivla role for IGFBP-1 in breast cancer cells is the known interaction with integrin α5β1." (PMID 32435229, 2020). "Molecular mechanistic understanding has revealed that IGFBP1 is a key component of G protein-coupled estrogen receptor 1 (encoded by GPER1) which regulated the sensitivity of breast cancer cells to tamoxifen, and the resistance induced by RG7388 (MDM2 inhibitor) in glioblastoma." (PMID 34737677, 2021). "However, several studies have revealed that low levels of IGFBP1 are related to increased risk of tumor progression and significant poor survival in breast cancer, colorectal cancer, and hepatocellular carcinoma." (PMID 33282953, 2020). "The data described in this contribution provides a link between the G protein-coupled estrogen receptor 1 (GPER1)-mediated IGFBP-1 accumulation associated with tamoxifen treatment in breast cancer cells with the alteration in growth factor signaling previously reported." (PMID 32435229, 2020). "The expression of IGFBP1 has close relationship with ovarian cancer, breast cancer, liver cancer, gastric cancer, pancreatic cancer, prostate cancer and esophageal squamous cell carcinoma." (PMID 37088808, 2023). "It has been shown that ovarian cancer and breast cancer patients with high expression of IGFBP1 have a better prognosis." (PMID 37088808, 2023). "Study reported that Insulin-like growth factor binding protein-1 (IGFBP-1) encodes a secretory protein associated with the risk of a variety of tumors, including in breast cancer, liver cancer, gastrointestinal cancer and endometrial cancer." (PMID 36468004, 2022). "Elevated IGFBP-1 expression has been reported in tamR MCF-7 and T-47D breast cancer cells, suggesting an association between tam resistance and IGFBP-1 accumulation." (PMID 35267540, 2022). "Previously, insulin-like growth factor binding protein-1 (IGFBP-1) induction in 4-hydroxytamoxifen (4-OHT)-treated breast cancer cells was shown to mediate the efficacy of 4-OHT." (PMID 32435229, 2020). "Differentiating the extracellular and intracellular roles of IGFBP-1 is necessary to fully understand the contribution of IGFBP-1 in breast cancer cells both during tamoxifen treatment and in the tamoxifen resistant state." (PMID 32435229, 2020). "The results reported herein suggest that IGFBP-1 has a prosurvival role in the tamoxifen resistant breast cancer cell and that sustained IGFBP-1 exposure is sufficient for the development tamoxifen resistance." (PMID 32435229, 2020). "MCF-7 and T-47D breast cancer cells stably transfected with and IGFBP-1 expression vector were generated (MCF7-BP1 and T47D-BP1) to determine the impact of breast cancer cell culture in the presence of increased IGFBP-1 expression." (PMID 32435229, 2020). "It has recently been reported that the inhibition of IGF-1R activation and the proliferation of breast cancer cells upon tamoxifen treatment is mediated by the accumulation of extracellular insulin-like growth factor binding protein 1 (IGFBP-1)." (PMID 32435229, 2020). "Taken together, these results provide evidence that IGFBP-1 contributes to the development of tamoxifen resistance in breast cancer cells and is a pro-survival signal for tamoxifen resistant breast cancer cells." (PMID 32435229, 2020). "Taken together, these data reveal a novel role for IGFBP-1 in the development of tamoxifen resistance in breast cancer cells." (PMID 32435229, 2020). "Taken together, these data provide support for the conclusion that IGFBP-1 is sufficient to confer tamoxifen resistance in breast cancer cells and is a prosurvival factor for chemoresistant breast cancer cells." (PMID 32435229, 2020).